CDK4 (cyclin dependent kinase 4)
Diseases named in the same sentence as CDK4 in open-access papers (continued):
Sharing a sentence is not in itself a finding about the gene and the disease.
cancer (continued). "It was suggested that complex events involved with CTs in the formation of derivative chromosomes contributed to the amplification of cancer-related genes, such as CCND1, CDK4, MDM2 and ERBB219." (PMID 33927198, 2021). "In light of the critical role of the pathway cyclin D/CDK4 and CDK6/Rb in cell cycle progression, one can easily argue the relevance of its deregulation in cancer cells." (PMID 34445095, 2021). "Overexpressed cyclin D1 (CCND1) can hyperactivate cyclin-dependent kinase 4 and 6 (CDK4/6) and induce cisplatin resistance in HNSC, TGCT and other cancers." (PMID 33995018, 2021). "To further evaluate the biological and inhibitory effects of NSC765600 and NSC765691 in cancer, we identified CCND1/CDK4/PLK1/CD44 as potential druggable candidates for both compounds by using online prediction tools." (PMID 34063946, 2021). "Abnormal regulation of the CDK4- and CDK6-cyclin D-INK4-retinoblastoma protein (Rb) signaling pathway is one of the most common aberrations noted in many human cancers, in particular, in GBMs, which cells show excessive CDK4/CDK6 activation." (PMID 34440090, 2021). "Resveratrol improves the sensitivity of BC chemotherapy and prevents the development of cancer by targeting miR-122-5, and then influences the expression of CDK2, CDK4, and CDK6, resulting in cell-cycle arrest." (PMID 32183020, 2020). "The relationship between ASPM and CDK4 or CCND1 and the related mechanism should be further explored, and perhaps the role and the mechanism are different in different kinds of cancers." (PMID 32742488, 2020). "Specific degradation of p27 from cyclin E/A-CDK2 complexes would be a cunning oncogenic mechanism, enabling cancer cells to hyperactivate CDK2, while simultaneously retaining high CDK4 activity." (PMID 33166394, 2020). "Therefore, a large fraction of patients with RB-deficient cancers may not benefit from a CDK4/6 inhibitor (CDK4/6i), suggesting the necessity for developing new strategies to improve the efficacy of CDK4/6i." (PMID 32249776, 2020). "Considering that CDK4/6 31 and FGFR 32 inhibitors are being tested in clinical trials for treatment of multi-type cancers, we subsequently investigated their expression and functions." (PMID 32194860, 2020). "Palbociclib is a selective inhibitor of CDK4 and CDK6 and it was the first inhibitor of CDKs that was approved as a cancer therapy in combination with letrozole, an aromatase inhibitor." (PMID 32373584, 2020). "As another example, the transcription of CDK4 is linked to tobacco mediated oral carcinogenesis and acts as a potent cyclin dependent Kinase 4 Regulatory Factor (KRF) and a potential cancer target." (PMID 32872541, 2020). "The best-established mechanism of mTOR activation in cancer is via PI3K/Akt signaling, but mTOR activity can also be stimulated by CDK4 and PIM kinases." (PMID 32391118, 2020). "The most frequent cMDT among the COSMIC cancer genes were observed for the E3 ubiquitin-protein ligases FBXW7 and MDM2, and the Cyclin-Dependent Kinase CDK4." (PMID 32879328, 2020). "The cancer models data demonstrate that simultaneous disruption of the acetyllysine binding function of BRD4 and kinase activities of PI3K and CDK4/6 improves efficacy." (PMID 32694708, 2020). "P276-00 is a novel inhibitor for CDK-1, CDK4 and CDK9 that has been tested in 16 tumor cell lines from different human cancers, showing a significant antiproliferative effect compared to cisplatin." (PMID 32850962, 2020). "Fascaplysin and similar alkaloids seem to mediate their activity by inhibition of cyclin-dependent kinase 4 (CDK4) and intercalation with dsDNA, which leads to a G1-phase cell cycle arrest and ultimately to the apoptotic cancer cell death." (PMID 33271756, 2020). "The reconstruction of pathways around estrogen receptor (ER), mTOR and cyclin D allowed the comparison of the effects of CDK4/6 and PI3K/AKT/mTOR inhibitors in metastatic HR+ cancer." (PMID 32351542, 2020).
cancer (continued). "The results showed that the expression of FBX8 in adjacent normal tissues was significantly higher than that in cancer tissues, while HIF-1α, CDK4, and C-Myc showed high expression in cancer tissues." (PMID 32796813, 2020). "We detect known cancer drivers in these putative double minutes, including MDM2 (four samples) and CDK4 (four samples)." (PMID 32025003, 2020). "In contrast, simultaneous targeting of multiple pathological pathways, implicating both BDs of BRD4 and additional cancer drivers such as PI3K and/or CDK4/6 notably increases efficacy." (PMID 32694708, 2020). "Indeed, recent studies suggest many cancer cells might be addicted to high CDK4/6 activity." (PMID 32307447, 2020). "In this study, we aim to deliver CDK4/6i PAL and autophagy inhibitor hydroxychloroquine sulfate (HCQ) considering both the aspects of cancer biology and chemical structure of active pharmaceutical ingredient (API)." (PMID 32843618, 2020). "Moreover, the compound exerted direct anticancer activity, both in vitro and in vivo experiments, on cancer cells by cell-cycle arrest at G0/G1 phase through induction of cell-cycle inhibitory protein p27 and decreased expression of cyclin-dependent kinase 4 (CDK4)." (PMID 32046125, 2020). "Clustering analysis of the frequency of events targeting CDK4, CCND1, CDKN2A, and RB1 indicates analyzed human cancers fall into five distinct groups separated largely by RB1 status and the co-occurrence of CCND1, CDK4, and CDKN2A." (PMID 32242058, 2020). "In cancer development, BRD4 was a stimulator for the expression of cell proliferation related genes, such as c-Myc, CyclinD1 and CDK4, as well as cell migration related genes, such as MMP-2 and MMP-9." (PMID 32640974, 2020). "And studies have shown that SAHA generally fights against cancer by upregulating the p21 (CDKN1A) cancer suppressor gene, PTEN, p27 and decreasing levels of pro-growth genes CDK2, CDK4, cyclin D1 and cyclin E." (PMID 32682428, 2020). "CDK4/6 inhibitors specifically accelerate the induction of cellular senescence by inhibiting CDK4/6-induced phosphorylation of RB, subsequently activate immunosurveillance by SASP, and effectively clear senescent cancer cells including HCC cells." (PMID 33330071, 2020). "In this study, we show that the CDK4/6 inhibitor abemaciclib inhibits PIM kinase and S6 phosphorylation in cancer cells and concurrent inhibition of PIM, CDK4, and CDK6 suppresses both S6 and Rb phosphorylation." (PMID 32391118, 2020). "They showed that combining CDK4/6 and PI3K inhibitors triggered cancer cell apoptosis in vitro and in PDX mice." (PMID 30959874, 2019). "CDK7 is considered as an attractive target for treating human cancer, as it controls the activity of key enzymes involved in cell cycle progression, including other cyclin-dependent kinases such as CDK1, CDK2, CDK4, and CDK6." (PMID 31076643, 2019). "Recently studies on developing CDK inhibitors to treat cancer have focused on palbociclib, abemaciclib, and ribociclib, which are selective CCND1/CDK4/6 inhibitors." (PMID 31349793, 2019). "The results showed that the expression of CDK4, CCT2, and MGAT1 in LMS tissues was significantly higher than that in adjacent tissues and an important member of the cancer signaling pathway." (PMID 32117430, 2019). "MiR-34a can antagonize many different oncogenic processes by silencing oncogenes, including cyclin-dependent kinase 4/6 (CDK4/6), SIRT1, and SOX2, which function in self-renewal, migratory potential, and chemoresistance in various types of cancers." (PMID 31174564, 2019).
cancer (continued). "This enzyme is co-distributed with BRG1 at highly acetylated promoters of genes such as CDK4, LIG1, or NEIL3, which are responsible for cancer cell growth and the removal of DNA damage." (PMID 31614656, 2019). "Some target genes of miR-124 have been described, such as ROCK1, SNAIL2, CDK4, CAV1, and ERK2, whose action can suppress cancer growth and metastasis." (PMID 31052530, 2019). "Mitotic signals stimulate CDK4 and CDK6 activities, which promote cancer cell proliferation through the entrance of G1 into the S phase in cell cycle." (PMID 31906234, 2019). "In fact, CDK4/6 and CCND1 form together a complex, which regulates cell cycle and has been for that reason covered in various cancer studies." (PMID 30976209, 2019). "CDK4/6 stabilize and activate FOXM1 by phosphorylation at multiple sites to protect cancer cells from senescence." (PMID 31430272, 2019). "It is known that components of the CDK4–cyclin and CDK6–cyclin complexes are frequently altered in cancer." (PMID 29464035, 2018). "To investigate how WTAP regulated the cell proliferation of RCC cancer cells, we used western blot to investigate the expression change of cell cycle related protein CDK2, CDK4 and CDK6 by the knockdown or overexpression of WTAP." (PMID 29482572, 2018). "Since drugs targeting cdk4 and EZH2 are entering clinical trials, we propose that they should be tested in the treatment of cancers that become resistant to first-line genotoxic therapies." (PMID 29415991, 2018). "Cyclin-dependent kinase 4 (CDK4) was reported as the main target of fascaplysin (IC50 of 0.35 μM), and accordingly, drug-treated cancer cell lines arrested preferentially in the G0/1 cell cycle phase." (PMID 30322180, 2018). "In cancer cells, CCND1 is upregulated and activates CDK4/6, whereas Rb is deactivated, resulting in the dysregulation of the DNA-damage repair system and acceleration of the cell cycle." (PMID 28225893, 2017). "The genes that were shared by three different cancers (i.e., FGFR3, EPAS1, SRC, and FOXD3) are shown in coral, and the genes that were shared by two types of cancers (i.e., PPARG, FOXO1, CDK4, NKX3-1, PIK3R1, PRKCB and EDNRB) are shown in light pink." (PMID 28178311, 2017). "A recent study demonstrated that PPi hubs can be identified for a variety of cancer-related genes, including MYC, STK11, RASSF1, and CDK4." (PMID 28362357, 2017). "We also show that clinically relevant INK mutants can be selected in cancer cells that inactivate CDK4 and CDK6 through different mechanisms and, as a result, also show differing abilities to displace Cdc37 bound to CDK4 or CDK6." (PMID 29091774, 2017). "Our study on ECC demonstrated that OCT4 promoted survivin expression to inhibit apoptosis in cancer cells and promoted CCND1 expression and activated CDK4/6 activity to accelerate cell cycle progression." (PMID 29069758, 2017). "miR-34 family members are well-known TS-miRs which repress the expression of several targets involved in regulation of cell cycle and proliferation, like BCL-2, Notch1, cyclin E2, cyclin-dependent kinases 4 and 6 (CDK4 and CDK6), in MM and other cancers." (PMID 29073933, 2017). "CDK4 and CDK2 are not only involved in the formation of tumor resistance but also the inhibitors of cyclin-dependent kinase which has been the anti-cancer agent used in clinic." (PMID 26900348, 2016). "When we integrate these complementary and orthogonal methods, we identify and evaluate CDK4 and XPO1 as potential therapeutic targets in this cancer." (PMID 27329820, 2016). "The results of apoptosis assays and cell cycle analysis demonstrated that compound 9a obviously inhibits the proliferation of MCF-7 cancer cells by inducing apoptosis and arresting the cell cycle at G1 phase via inhibition of CDK2 and CDK4." (PMID 26901182, 2016).
cancer (continued). "Other hTERT activation pathways that are frequently deregulated in various cancer settings include those influenced by CDK2 and CDK4 and AKT, whereas deregulated repression pathways include those influenced by TGFβ, TNFα, and other cell cycle inhibitors." (PMID 25869441, 2015). "CDK4 inhibitors (CDK4i) earned Breakthrough Therapy Designation from the FDA last year and are entering phase III clinical trials in several cancers." (PMID 25803170, 2015). "Previous studies showed that miR-34a targets the oncogenes CDK4, CDK6, CCND1, MET, and BCL2, whereas miR-497 targets the oncogenes CCND2 and BCL2 in various types of cancer." (PMID 25909221, 2015). "Since miR-34a suppresses many oncogenes and cancer stem cell markers including CD44, CDK4, CDK6, c-Met, Notch-1, Notch-2, SIRT1 and DLL1 as its target genes, miR-34a plays important roles in cancer stem cells." (PMID 26580663, 2015). "First, cancer genome sequencing has demonstrated disruption of this pathway through CDKN2A deletion, a potential biomarker of sensitivity to CDK4/6 inhibitors, in approximately 13–30 percent of Ewing sarcoma tumors." (PMID 26337082, 2015). "In cancers that have genomic driver insults in CDKN2A or CDKN2B, inhibition of CDK4/6 is likely to be a therapeutic option worth investigating." (PMID 26634163, 2015). "It will be of great clinical importance to reveal which cancer genotypes correspond to cell cycle arrest, or even senescence and apoptosis, in response to inhibitor treatment, and which bypass routes may be used by cancer cells to acquire resistance to CDK4/6-specific inhibitors." (PMID 25562820, 2015). "With regard to the miR-195/497 cluster, it has been shown that miR-195 was downregulated in several cancers and inhibited glucose uptake, proliferation, and cell cycle by targeting GLUT3 and CDK4 in BC." (PMID 24520312, 2014). "In this study, we demonstrate that miR-188 exerts anti-cancer potential via downregulating multiple G1/S related genes, including CCND1, CCND3, CCNE1, CCNA2, CDK2 and CDK4." (PMID 25304455, 2014). "In particular, four genes within pathways in cancer were differentially expressed in the same direction under all the three conditions, including HSP90B1, ARAF, and RUNX1, being downregulated, and CDK4, being upregulated under these three manipulations." (PMID 25007077, 2014). "Molecules such as Her2, EGFR, VEGFR, ALK, AKT, p52, cyclin D1, Met, Cdk4, HIF-1α or MMP2 which play important roles as oncogenes and are involved in essential pathways of cancer are described to be client proteins of HSP90." (PMID 24978439, 2014). "Western blotting revealed that CDK1, CDK2, CDK4 and CDK6 proteins were expressed at much higher levels in the carcinoma tissues than the matched normal tissues." (PMID 24765199, 2014). "PD is a highly selective, orally administered inhibitor of both CDK4 and CDK6 kinase activity and is currently being evaluated in clinical trials for a variety of adult cancers." (PMID 24098593, 2013). "In the cancer cells, Rb is phosphorylated on CDK2 phosphorylation sites as well as CDK4 phosphorylation sites, whereas our data showed that Rb phosphorylation on the CDK2-specific phosphorylation site, threonine 821, was not induced by TNF-α treatment (day 6)." (PMID 24302570, 2013). "Among them, the following well-known cancer genes were found: MET, CDK4, MDM4, EGFR and PIK3CA (amplifications), and CDKN2A, MLLT3, HRAS, CARS and NF1 (deletions)." (PMID 23408991, 2013). "The findings from our study provide mechanistic insights into the anti-cancer activity of P276-00 and its effect on CCND1/CDK4/P16/pRB/E2F signaling cascade in FaDu cells." (PMID 23414419, 2013). "SAIC also identified many other cancer driver genes within individual chromosomes (ST 3), such as SKIL, CDK4, PIK3CA, PTEN, FGD4, FGFR1." (PMID 22839576, 2012).
cancer (continued). "Overexpressed genes in the PP adipose tissue of cancer patients that are involved in cell cycle and proliferation include PLCB1, that modulates cyclin D3 and CDK4 in response to the IGF-1 mitogenic stimulus or TPPP3, that regulates G2-M and G1-S transitions." (PMID 23009291, 2012). "Our results reveal that miR P-27-5p targets and negatively regulates CDK4, which in turn suppresses RB1 phosphorylation, thereby preventing the progression of cancer cell cycle and promoting G1 arrest." (PMID 22754369, 2012). "Among the key changes in the cell cycle in normal to cancer transition are the differential expression of cyclins (A and B) and cyclin-dependent kinases (CDK1 and CDK4/6 complex)." (PMID 20875095, 2010). "Of the proliferative factors analysed (PCNA, cyclin A, cyclin D, the cyclin-dependent kinases cdk2 and cdk4, cell cycle phases) only PCNA and cyclin A (CCNA) exhibited a relationship to sensitivity/resistance and were down-regulated in resistant carcinomas." (PMID 12177790, 2002). "Clinically, high ZDHHC17 expression is positively correlated with non-response to anti-PD-1 therapies in cancer patients, partially due to CDK4-mediated repression of PD-L1." (PMID 42133178, 2026). "By simultaneously inhibiting CDK4/6 and managing CDK2 activity, it may be possible to induce cell cycle arrest more effectively and prevent the proliferation of cancer cells that have adapted to evade conventional regulatory mechanisms." (PMID 41465342, 2025). "Although this CDK4/6-Rb pathway is frequently altered in cancers, it is not strictly essential for cell division, as deletion of Ccnd1, Cdk4, or Cdk6 is not embryonically lethal in mice." (PMID 41226361, 2025). "This may be an important handicap of these models for the investigation of the role of CDK4 and CDK6 and their inhibition as an anti-cancer strategy, given that, as discussed, inhibitors of CDK4/6 affect immune processes." (PMID 40699853, 2025). "Other targets of phosphorylation of CDK4 and CDK6 may also be of therapeutic interest in cancer, including transcription factors FOXM1, SMAD3 and NFAT4." (PMID 40699853, 2025). "As post-treatment resistant cancer cells show activation of the ERBB signaling pathway, we took a parallel experimental approach to test whether endocrine and CDK4/6i treatments drive compensatory ERBB receptor expression in vitro." (PMID 40341770, 2025). "Collectively, our preclinical study suggests that targeting CDK4/6 could serve as a promising therapeutic approach for treating CRC and other cancers characterized by overexpression of wild‐type DUB3 and YAP1." (PMID 39968498, 2025). "Cyclin-dependent kinase 4/6 (CDK4/6) inhibitors, which are designed for targeting retinoblastoma (RB) protein phosphorylation and thereby block cancer cell growth, have been approved by the FDA as frontline targeted therapies for hormone receptor-positive (HR+), HER2-negative breast cancer." (PMID 41154395, 2025). "For more patients to benefit from CDK4/6 inhibitor therapy, research is needed to determine how cancer cells of CDK4/6 inhibitor resistant tumors modify non-cancer regulatory communications to produce a supportive TME." (PMID 40032842, 2025). "We therefore have tried to summarize below the CDK4 and CDK6 shared activities in cancer progression and at the same time highlighting which are the functions that could be considered specific for each kinase." (PMID 39800748, 2025). "Our characterization of this hotspot mutation, leveraging primary human keratinocytes and the Ras-CDK4 cSCC model, demonstrates that the SRCAP-1879 truncation is sufficient to dysregulate gene expression in a cell-state-dependent manner and promote cancer invasion with the induction of MMP9." (PMID 40858549, 2025).